YY1 (YY1 transcription factor)
Diseases named in the same sentence as YY1 in open-access papers (continued):
Sharing a sentence is not in itself a finding about the gene and the disease.
Obesity (15 papers, 2012 to 2025). Accumulation of substantial excess body fat. "Emerging evidence implicates YY1 as a key pathogenic factor in the development of metabolic disorders, including insulin resistance, obesity, T2D, and metabolic dysfunction-associated steatotic liver disease (MASLD)." (PMID 41459495, 2025). "The loss of the YY1 protein in mice can protect against diet-induced obesity and increase energy consumption." (PMID 37237371, 2023). "Taken together, our findings demonstrate that betaine can improve obesity and associated MS via the gut microbiota-derived miR-378a/YY1 regulatory axis, and reveal a novel mechanism by which gut microbiota improve host health." (PMID 33550882, 2021). "Moreover, we found that suppressing FXR expression by Yin Yang 1 (YY1) increases obesity-associated hepatosteatosis." (PMID 34745420, 2021). "Nevertheless, future studies are needed to further dissect the mechanisms linking RAS to YY1 expression, and further validate the role of Ang II- regulated miRNAs in obesity-linked ER stress, all of which are worth investigation but beyond the scope of this manuscript." (PMID 31186446, 2019). "In the sections that follow, we critically examine the emerging roles of RKIP and YY1 in the context of metabolic disease, highlight current knowledge gaps, and discuss potential therapeutic implications for obesity, T2D, and cardiovascular disorders." (PMID 41459495, 2025). "Nonetheless, given their functional relevance across key metabolic tissues and their regulatory roles throughout the spectrum of metabolic disease, both RKIP and YY1 represent viable and compelling targets for therapeutic intervention in obesity and T2D." (PMID 41459495, 2025). "Disruption of this balance, as observed in obesity and T2D, favors YY1-mediated inflammation and metabolic dysfunction, while RKIP downregulation eliminates critical inhibitory checkpoints." (PMID 41459495, 2025). "Under conditions of chronic nutrient excess, such as obesity and T2D, YY1 expression and function become dysregulated, contributing to elevated inflammation, impaired insulin signaling, and disrupted lipid homeostasis." (PMID 41459495, 2025). "Betaine, a major methyl donor, induced browning of inguinal white adipose tissue (iWAT) and activation of brown adipose tissue (BAT) by modulating the miR-378a/YY1 axis, thereby improving obesity and its complications." (PMID 39609876, 2024). "Yin Yang 1 (YY1), a nuclear transcription factor, has been implicated in metabolic diseases such as nonalcoholic fatty liver disease (NAFLD), obesity, and diabetic nephropathy." (PMID 39596325, 2024). "YY1 has also been involved in obesity by promoting triglyceride accumulation—and it is up-regulated in the hepatic tissue of both obese animals and NAFLD patients." (PMID 36768322, 2023). "Supporting previous findings that YY1 contributes to HFD-induced obesity, improvement in lipid metabolism and glucose homeostasis by betaine or miR-378a family was obviously reduced by increasing YY1." (PMID 33550882, 2021). "The notion of modulation of YY-1 in states of obesity is strengthened by our in vitro cell culture studies where a reduction in its expression was seen following exposure to palmitate-BSA and accentuated by concomitant transfection of MIOX-pcDNA." (PMID 32708636, 2020). "Mice lacking YY1 in adipose tissue were strongly protected against diet-induced obesity.YY1-deficient mice exhibited increased energy expenditure and oxygen consumption in beige and white fat depots." (PMID 41459495, 2025). "However, obesity-associated oxidative stress and hyperinsulinemia downregulate RKIP expression, weakening its regulatory control and allowing unchecked YY1 activity." (PMID 41459495, 2025).
Obesity (continued). "Thus, it can be concluded that betaine ameliorates obesity and related metabolic syndrome through the gut microbiota‐derived miR‐378a/YY1 regulatory axis, revealing a novel mechanism whereby gut microbiota enhances host health." (PMID 40255548, 2025). "Based on systematic overexpression of miR-378a and YY1 in vivo, whether hepatic and adipose tissues are only targets of microbiota-derived signals during prevention of betaine on obesity remains largely unknown." (PMID 33550882, 2021). "In lean mice, YY1 was predicted to regulate 46 of the ovarian proteins identified to be altered by DMBA exposure and 84 of the proteins that were altered basally by HFHS-induced obesity." (PMID 39910959, 2025).
rheumatoid arthritis (15 papers, 2016 to 2025). A chronic, systemic autoimmune disorder characterized by inflammation in the synovial membranes and articular surfaces. "In rheumatoid arthritis, YY1 has been found to promote pathogenic Th17 cell differentiation by interacting with T-bet and participating in the pathophysiological process." (PMID 40458393, 2025). "For instance, YY1 controls Th17 cell pathogenicity in rheumatoid arthritis by binding to the promoter region of the transcription factor T-bet and interacting with T-bet protein." (PMID 40458393, 2025). "In inflammation-related diseases such as rheumatoid arthritis and ulcerative colitis, YY1 promotes pathophysiological processes by interacting with associated regulators." (PMID 40458393, 2025). "Antioxidant stress presents new mechanisms in mediating RA ferroptosis, where SIRT1 is transcriptionally suppressed by YY1 and inhibits ferroptosis in rheumatoid arthritis." (PMID 38965216, 2024). "In rheumatoid arthritis, the overexpression of miR-410-3p restricted proliferation, promoted apoptosis by inhibiting YY1." (PMID 34872453, 2021). "TNF‐α and IL‐1β promoted YY1 expression in the fibroblast‐like synoviocytes of rheumatoid arthritis patients." (PMID 29928577, 2018). "It has been proved that YY1 plays an important role in cancers and rheumatoid arthritis (RA)." (PMID 38156385, 2023).
non-small cell lung carcinoma (13 papers, 2020 to 2025). A group of at least three distinct histological types of lung cancer, including non-small cell squamous cell carcinoma, adenocarcinoma, and large cell carcinoma. "eIF3a sustains non-small-cell lung cancer stem cell-like properties by promoting the YY1-mediated transcriptional activation of β-catenin." (PMID 38275418, 2024). "In contrast, ubiquitin specific protease 21 (USP21) stabilizes YY1 in non-small-cell lung cancer cells via mediating its deubiquitination." (PMID 35103856, 2022). "The USP21/YY1/SNHG16 axis is involved in the proliferation, migration, and invasion of non-small-cell lung cancer (NSCLC)." (PMID 36983670, 2023). "Overexpression of YY1 can induce DNAJB4 transcription by directly binding to the promoter region, which inhibits the invasive ability of non-small-cell lung carcinoma (NSCLC) cells." (PMID 36499297, 2022). "For example, miR-29a, which was previously reported to inhibit tumorigenicity in non-small cell lung cancer (NSCLC) by downregulating DNA methyltransferase (DNMT)3A and 3B, can suppress YY1 mRNA and protein expression levels in lung tumor cells, resulting in suppressed proliferation and migration." (PMID 37444616, 2023). "However, another study reported that USP21 promotes non-small cell lung cancer (NSCLC) cell proliferation, migration, and invasion, including A549 cells, by deubiquitinating and stabilizing an oncoprotein, Yin Yang-1 (YY1)." (PMID 37743467, 2023).
rhabdomyosarcoma (13 papers, 2010 to 2025). A rare aggressive malignant mesenchymal neoplasm arising from skeletal muscle. "Other studies have shown that miR-29c is epigenetically silenced by an activated NF-κB/YY1 complex, which functions as a suppressor of the miR-29c promoter in rhabdomyosarcoma." (PMID 38994944, 2024). "Recently, it has been shown that miR-29 expression in rhabdomyosarcoma is lost via inhibition due to NF-kB and YY1 “expression forming” a state of uncontrolled regulation." (PMID 31040909, 2019). "YY1 is a ubiquitously expressed transcription factor, and the YY1-miRNA axis, as NF-kB- YY1-miR-29 signaling axis in rhabdomyosarcoma and YY1-miR-1-Pax 7 axis in skeletal myogenesis, has been identified in different cellular processes." (PMID 26104682, 2015). "Mir-29b, which is regulated by the NF-κB/YY1 pathway and whose abnormal expression may contribute to myogenesis and rhabdomyosarcoma, acts as a tumor suppressor by downregulating the transcription factor Yin Yang 1 (YY1)." (PMID 32276464, 2020). "Interesting, YY1 and CDK6 have been demonstrated as direct targets of miR-29 by the reporter assay in rhabdomyosarcoma and lymphoma." (PMID 35628336, 2022). "In rhabdomyosarcoma on the other hand, there is epigenetic silencing of miRNA29 through activation of the NFKB-YY1 pathway and as a result there is reduced silencing of YY1 by miRNA 29, and in the context of higher YY1, myogenic differentiation does not progress." (PMID 26204834, 2015). "Parenthetically, YY1 in this collaboration with JARID2 can recruit EZH2 and HDAC 1 to the promoter region leading to a block in differentiation, partially via the downregulation of miR-29b2 and miR-29c and by inhibiting MyoD, favoring rhabdomyosarcoma cell proliferation over differentiation." (PMID 27323832, 2016).
lung adenocarcinoma (12 papers, 2016 to 2025). A carcinoma that arises from the lung and is characterized by the presence of malignant glandular epithelial cells. "Third, YY1 was analyzed in six cases of advanced EGFR-mutant lung adenocarcinoma with disease relapse following first-line EGFR inhibitor treatment, which showed that YY1 levels rebounded to baseline in recurrent tumors." (PMID 39604408, 2024). "Immunohistochemical analysis on a wide spectrum of clinical specimens revealed that YY1 was ubiquitously expressed across lung adenocarcinomas and exhibited anticipated fluctuation in response to corresponding RTK/MAPK inhibition." (PMID 39604408, 2024). "In order to validate the crucial involvement of YY1 in HDAC2-mediated cellular migration, we conducted a deletion of YY1 in HDAC2 overexpressed lung adenocarcinoma cells." (PMID 37495623, 2023). "These outcomes provide evidence that YY1 serves as a functional collaborator with HDAC2 in the migration of lung adenocarcinoma cells, and emphasize the potential for targeting HDAC2-YY1 interactions as a means of developing innovative therapeutic approaches." (PMID 37495623, 2023). "The findings of this investigation unveil a novel role of HDAC2/YY1 in lung adenocarcinoma migration." (PMID 37495623, 2023). "The identification of HDAC2's interaction with YY1 in lung adenocarcinoma cells prompted an investigation into the involvement of YY1 in lung adenocarcinoma migration." (PMID 37495623, 2023). "By looking at specific stages of lung adenocarcinoma evolution in a genetic mouse model, single-RNA seq data showed that Yy1 had an increased expression from NT to late adenoma stages." (PMID 35205667, 2022). "When compared to normal tissues, YY1 total protein expression was higher in the primary tissues of breast, ovarian, colon, and lung adenocarcinoma and lower in the primary tissues of clear cell renal cell carcinoma (clear cell RCC) and UCEC (P < 0.001)." (PMID 35791393, 2022). "In comparison to the normal control group, YY1 total protein expression was shown to be greater in primary tissues of breast, ovarian, colon, and lung adenocarcinoma and lower in primary tissues of clear cell RCC and UCEC." (PMID 35791393, 2022). "As YY1 was found to be more highly expressed in the lung and lung adenocarcinoma, it was selected for further analysis." (PMID 36268014, 2022). "As for lung adenocarcinoma, YY1 was significantly higher expressed in LUAD tissues than in non‐tumour tissues at mRNA and protein levels." (PMID 32557953, 2020). "Indeed, YY1 gene expression was unrelated to EGFR status in lung adenocarcinoma from the Cancer Genome Atlas." (PMID 39604408, 2024). "The present study aimed to examine the involvement of HDACi in TGF-β-mediated cell migration and ascertain the significance of HDAC2 in lung adenocarcinoma cell migration by means of its interaction with YY1 and repression of EMT-related molecule transcriptional activity." (PMID 37495623, 2023). "Furthermore, a recent investigation has uncovered the indispensable role of the HDAC2/YY1 complex in lung adenocarcinoma metastasis." (PMID 37495623, 2023). "MRPL42 is activated by YY1 to promote the progression of lung adenocarcinoma." (PMID 34868337, 2021). "In order to examine the clinical significance of YY1 and HDAC2 in lung adenocarcinoma, we conducted an analysis of their expression levels in clinical patient samples." (PMID 37495623, 2023). "To determine whether the negative regulation of YY1 expression by miR-125a-3p observed in HEK293T cells also occurred in lung epithelial cells, we used, as a cell model, the A549 human lung adenocarcinoma cell line to test endogenous YY1 expression in response to a miR-125a-3p mimic." (PMID 33158935, 2020).
triple-negative breast carcinoma (12 papers, 2019 to 2025). An invasive breast carcinoma which is negative for expression of estrogen receptor (ER), progesterone receptor (PR), and human epidermal growth factor receptor 2 (HER2). "For triple-negative breast cancer, YY1 has also been identified as a critical promoter for tumor proliferation and invasion." (PMID 38831379, 2024). "Additionally, a recent study reported that KCNQ1OT1 participated in Yin Yang 1 (YY1)-mediated tumor-promoting effects on Triple-negative breast cancer (TNBC) through its interactions with DNMT1, in support of role of KCNQ1OT1 in TNBC." (PMID 36100884, 2022). "It has been reported that YY1 functions as an oncogene in triple negative breast cancer." (PMID 32249890, 2020). "Hence, YY1-dependent repression of LINC00152 expression leads to elevated PTEN levels and suggested that YY1/LINC00152/PTEN axis plays an important tumor suppressive role in triple negative breast cancer." (PMID 31824839, 2019). "In triple-negative breast cancer, the transcription factor YIN-YANG 1 (YY1) was found to inhibit the transcription of CYTOR, thereby acting as an anticancer agent." (PMID 39058104, 2024).
COVID-19 (11 papers, 2022 to 2023). A disease caused by infection with severe acute respiratory syndrome coronavirus 2. "In obese mouse models, YY1 was markedly upregulated, which may provide us with the possible cause of increased mortality in COVID-19 patients with MUO." (PMID 37877121, 2023). "The identified TFs, such as FOXC1, GATA2, YY1, FOXL1, FOXO3, STAT1 and STAT3, are associated with COVID-19." (PMID 37261353, 2023). "in a study identified YY1, CREB1, and GATA2 to be critical TFs involved in the regulation of COVID-19 patients at the genetic level in their pathogenesis." (PMID 37283761, 2023). "A recent study about the genomics of COVID-19 showed that TFs like FOXC1, GATA2, YY1, FOXL1, and NFKB1 regulated the inflammatory network in SARS-CoV-2 infections." (PMID 35747501, 2022). "In COVID-19 interaction, the TF–miRNA network showed that E2F1, MAX, EGR1, YY1, and SRF were the highly expressed TFs, and hsa-miR-19b, hsa-miR-495, hsa-miR-340, hsa-miR-101, and hsa-miR-19a were among significant miRNAs." (PMID 36059456, 2022). "FOXC1, YY1, GATA2, FOXL, STAT1 and STAT3 are important TFs for COVID-19." (PMID 37261353, 2023). "In our analysis, FOXC1, GATA2, YY1, and PPARG may play a role in the development of COVID-19 and IS." (PMID 37184686, 2023). "Furthermore, our research indicates that transcription factors FOXC1, GATA2, YY1, NR2C2, and E2F4 were overexpressed in common DEGs of psychiatric disorders and COVID-19." (PMID 35185890, 2022). "In COVID-19 patients, the DEG–miRNA, and DEG–transcription factors (TFs) interactions network analysis revealed that E2F1, MAX, EGR1, YY1, and SRF were the highly expressed TFs, whereas hsa-miR-19b, hsa-miR-495, hsa-miR-340, hsa-miR-101, and hsa-miR-19a were the overexpressed miRNAs." (PMID 36059456, 2022).
Gabriele de Vries syndrome (11 papers, 2019 to 2025). "POGZ gene codes for pogo transposable element-derived zinc-finger protein and YY1 gene regulates transcription, chromatin, and RNA-binding proteins that have been associated with White Sutton and Gabriele-de-Vries syndromes, in recent data." (PMID 39775551, 2025). "Abnormal looping of genetic regulatory elements was observed in patients with Gabriele-de Vries syndrome, caused by mutations in the yy1 gene, but can also happen in cells with the wild-type yy1 in conditions that affect its dimerization propensity." (PMID 37686614, 2023). "Gabriele-de Vries syndrome is a rare autosomal dominant genetic disease caused by de novo pathogenic variants in the Yin Yang 1 (YY1) gene." (PMID 37189872, 2023). "It is worth noting that mutations/deletions in YY1 are responsible for the Gabriele-De Vries syndrome, an autosomal dominant neurodevelopmental disorder characterized by intellectual disability, delayed psychomotor development and frequent autistic symptoms." (PMID 31031802, 2019). "Interestingly, YY1 de novo mutations cause Gabriele-de Vries syndrome, a form of syndromic intellectual disability characterized by a complex movement disorder, including ataxia and progressive dystonia along with prominent laryngeal involvement." (PMID 38042508, 2024). "Gabrielle-De Vries syndrome (GADEVS, OMIM #617557) (mutations of YY1 gene) has been also associated." (PMID 34202860, 2021). "Heterozygous mutation involving the YY1 gene located on chr14:100,239,143-100,282,787 (OMIM #617557) can cause Gabriele-de Vries syndrome, characterized by mild-to-profound DD/ID in all affected individuals and a broad spectrum of morphological and functional abnormalities." (PMID 34573370, 2021). "Moreover, YY1 is not only recognized as being crucially involved in CNS development (as notably shown in the inherited brain disorder “Gabriel-de Vries syndrome”), but also as exerting major functions in the immune system." (PMID 31031802, 2019).